FAP (fibroblast activation protein alpha)
Diseases named in the same sentence as FAP in open-access papers (continued):
Sharing a sentence is not in itself a finding about the gene and the disease.
Arthritis (39 papers, 2006 to 2026). Inflammation of a joint. "Deletion of systemic and local FAPα+ fibroblasts lead to protection associated with reduced leukocyte infiltration, inflammatory mediators, and joint damage in mouse models of arthritis." (PMID 36926329, 2023). "However, knocking out FAPα expressing fibroblasts in mice did not suppress inflammation but reduced the extent of tissue damage, confirming the pathogenic role of FAPα in arthritis." (PMID 38895122, 2024). "The deletion of FAPα+ cells resulted in a decrease in leukocyte infiltration, was negatively correlated with the severity of joint inflammation, and was associated with a decrease in the number of fibroblasts without a significant change in the number of pericytes." (PMID 38136590, 2023). "Since arthritis and osteophytes could express FAP and this surgery could also cause damage in the joint, it was assumed that degeneration occurred in this model." (PMID 35725436, 2022). "Fibroblast Activation Protein (FAP) is a membrane-bound serine protease whose expression is often elevated in activated fibroblasts associated with tissue remodeling in various common diseases such as cancer, arthritis and fibrosis." (PMID 28970566, 2017). "Moreover, FAP is associated with cell migration and cell invasiveness and has been linked to several diseases, including cancer and arthritis." (PMID 25600705, 2015). "Since the formation of invadopodia-like structures by arthritis SF has been associated with cartilage degradation and additionally, FAP has been localized on invadopodia, we first investigated the expression of FAP in RA." (PMID 25600705, 2015). "In addition, FAPα maps to a chromosomal region containing collagen-induced arthritis linked susceptibility loci, which is also consistent with a role in arthritis." (PMID 16507127, 2006). "Having identified an association between FAP expression and the earliest clinically evident stage of RA, we tested the hypothesis that stromal markers would differentiate between the key prognostic outcomes of persistence or resolution in early arthritis." (PMID 28793332, 2017). "The authors used anti-FAP antibody 28H1 conjugated with the photosensitizer IRDye700DX to successfully induce FAP-specific cell death and delayed arthritis." (PMID 40607439, 2025). "Animal studies have also demonstrated that the depletion of FAP-positive FLS can attenuate the progression of arthritis." (PMID 40607439, 2025). "Fibroblast activation protein-α (FAP) is a type II transmembrane serine protease primarily expressed during pathologies such as cancer, fibrosis, and arthritis." (PMID 38540158, 2024). "Of note, inducible depletion of both subsets ameliorated experimental arthritis, whereas adoptive transfer of FAPα+THY1+ fibroblasts resulted in more severe, persistent disease." (PMID 39906351, 2024). "Fibroblast activation protein (FAP) is a 97 kDa type II transmembrane serine protease with elevated expression in reactive stromal fibroblasts found in cancer, arthritis, fibrosis, and interstitial lung disease." (PMID 40603575, 2024). "This compound can accumulate in inflamed joints and induce local FAPα+ cell death, which moderately delayed the development of arthritis in CIA mice." (PMID 38783357, 2024). "A series of fluorescent FAPI conjugates were synthesized to understand the impact of internalization and plasma kinetics on in vivo FAP molecular imaging in preclinical arthritis models." (PMID 40603575, 2024). "Previous findings showed that FAP was hard to be detected in normal tissues but significantly up-regulated in remodeling sites like fibrosis, atherosclerosis, arthritis and embryonic tissues." (PMID 37325617, 2023). "The synovial expression of FAPα was either low or undetectable at rest, increased significantly during the course of arthritis, and correlated with the severity of ankle swelling." (PMID 38136590, 2023).
Arthritis (continued). "In this study, we have shown that an mRNA-LNP based vaccine against FAP reduced the severity of experimental arthritis in mice." (PMID 37818347, 2023). "Fibroblast activation protein (FAP) is a type-II membrane bound glycoprotein specifically expressed by activated fibroblasts almost exclusively in pathological conditions including arthritis, fibrosis and cancer." (PMID 39355017, 2023). "It would be worth noting that the adoptive transfer of FAPα+THY1+ cells induced inflammation while FAPα+THY1- cells induced joint destruction in the mouse model of serum transfer-induced arthritis." (PMID 36982247, 2023). "It is expected that CAR T cells against FAP will also display therapeutic effects in arthritis models." (PMID 35252279, 2022). "All these observations support the feasibility and safety for a treatment of arthritis by depleting FAP expressing fibroblasts." (PMID 35252279, 2022). "Injecting PDPN+FAPα+THY1− or PDPN+FAPα+THY1+ cells into the inflamed ankle joint of mice is a different method for investigating arthritis degeneration processes." (PMID 36232468, 2022). "For instance, chronic inflammation, arthritis, fibrosis and ischemic heart tissue after a myocardial infarction are FAP-positive diseases." (PMID 34638433, 2021). "A radiolabeled anti–FAP antibody has even been used as a noninvasive strategy to monitor the course of collagen-induced arthritis in mice." (PMID 32842604, 2020). "For the therapeutic drug development, targeted photodynamic therapy (tPDT) using the anti-FAP antibody 28H1 coupled to the photosensitizer IRDye700DX moderately delayed the collagen-induced arthritis development in mice." (PMID 32842604, 2020). "Stromal cell markers CD55, CD248, FAP and podoplanin are expressed in ST in the earliest stage of arthritis." (PMID 28793332, 2017). "It is most likely that high expression of FAP and β1 integrins on arthritis SF leads to increased attachment of SF to cartilage matrix, thus promoting cartilage degradation." (PMID 25600705, 2015). "In a murine collagen-induced arthritis model, gene-expression profiling using the Mu11K array (Affymetrix) showed a seven- fold increase in FAPα gene expression together with MMP expression in inflamed, compared to non-inflamed, paws." (PMID 16507127, 2006). "Consequently, studies have indicated that radiolabeled anti-FAP antibodies can serve as biomarkers to display disease activity and monitor treatment responses in arthritis, as seen in experimental arthritis models." (PMID 40607439, 2025). "Single-cell transcriptomics in the synovium of serum transfer-induced arthritis (STIA) mice revealed two anatomically distinct fibroblast activation protein-α (FAPα)+ subpopulations, differentiated by the expression of thymus cell antigen 1 (THY1, also known as CD90)." (PMID 39906351, 2024). "Over the past two decades, the most active area of study of FAPα has been oncology, but the role of FAPα is also being actively studied in the pathogenesis of fibrotic diseases, including arthritis, IPF, atherosclerosis, and fibrotic conditions of the liver and colon." (PMID 38136590, 2023). "We tested whether FAP can serve as a molecular target to modulate synovial fibroblasts for therapy in experimental arthritis." (PMID 37818347, 2023). "High expression of FAP also occurs in chronic inflammation, fibrosis, arthritis, atherosclerotic plaques and cardiac fibrosis 6-9, which results in a compromised sensitivity/selectivity in distinguishing cancer from other FAP-positive diseases, such as chronic inflammation and fibrosis." (PMID 36276644, 2022). "Furthermore, depletion of FAP expressing fibroblasts in serum transfer arthritis model reduced arthritis severity." (PMID 35252279, 2022). "Thus, FAP expressing cells were depleted by injection of diphtheria toxin during arthritis in transgenic FAP luciferase diphtheria toxin receptor reporter mice." (PMID 35252279, 2022).
Arthritis (continued). "In addition to CAFs, intense FAP expression is also related to fibrosis, arthritis, atherosclerosis, and autoimmune diseases." (PMID 35198057, 2022). "Furthermore, the expression of FAP due to wound healing, arthritis, inflammation and cirrhotic liver would interfere with the results." (PMID 33777814, 2021). "Surprisingly, FAP-deficiency in hTNFtg mice did not lead to significant reduction of signs of arthritis as compared to hTNFtg mice." (PMID 25600705, 2015). "Our study points to a so far unknown role of FAP in fibroblast-mediated cartilage degradation in arthritis." (PMID 25600705, 2015). "FAP has mainly been found in pathological environments (fibrosis, keloids, cancer and arthritis)." (PMID 25816202, 2015). "As such, the biomarker could be a useful tool in other diseases, as FAP has been shown to be upregulated and influential in multiple types of cancer as well as non-cancerous diseases including acute coronary syndrome, fibrosis, and arthritis." (PMID 38540158, 2024). "We then tested whether an mRNA vaccine against FAP will have therapeutic effects on arthritis." (PMID 37818347, 2023). "Moreover, levels of FAP expression in CIA joints is correlated with the severity of arthritis." (PMID 35252279, 2022). "As in human arthritis, blockade of TNF and IL-17A significantly reduced FAP tracer uptake in the joints, again with more pronounced effects for IL-17i than for TNFi treatment." (PMID 39586916, 2025). "A vaccine with the consensus FAPα mRNA encapsulated in a lipid nanoparticle (cFAP mRNA-LNP) prevented disease onset and arthritis development in a mouse model of RA." (PMID 38783357, 2024). "FAP + THY+ fibroblasts were found to be responsible for severe and persistent inflammation in arthritis." (PMID 37443817, 2023). "cFAP mRNA-LNP vaccine provoked immune response to cFAP and mouse FAP (mFAP); prevented onset of CIA in 40% of mice and significantly reduced the severity of arthritis." (PMID 37818347, 2023). "We first investigated the expression of FAP in two arthritis models: CIA in DBA/1 mice and zymosan-induced arthritis in SKG mice." (PMID 37818347, 2023). "In humans, studies have confirmed that CD248 and PPDN (together with FAP and DAF/CD55) are highly expressed in the synovial tissue in the early stage of arthritis." (PMID 37298499, 2023). "GM-CSF is highly expressed by sublining CD90+ FAP+ synovial fibroblasts, CD90+ activated endothelium and CD163+ macrophages in different types of arthritis." (PMID 33679701, 2020). "It is interesting and intriguing that FAP mRNA-LNP vaccination did not prevent onset of CAIA although it reduced arthritis severity." (PMID 37818347, 2023). "FAP+THY+ fibroblasts were involved in severe and persistent inflammation in arthritis." (PMID 37443817, 2023). "Data from the most recent study confirmed that depletion of FAP expressing fibroblasts in an arthritis model was not toxic." (PMID 35252279, 2022). "Similarly, we have demonstrated that FAP is highly expressed in the synovium of arthritic joints in murine models of RA, collagen-induced arthritis (CIA) and arthritis in SKG mice." (PMID 35252279, 2022). "Studying the biodistribution of a humanised anti-FAP antibody in patients with advanced or metastatic FAP-positive cancer, a minor low-grade uptake in the knees and shoulders of three patients without clinical symptoms of arthritis was observed." (PMID 17105646, 2006). "ST from 56 patients included in two different early arthritis cohorts and 7 non-inflammatory controls was analysed using immunofluorescence to detect stromal markers CD55, CD248, fibroblast activation protein (FAP) and podoplanin." (PMID 28793332, 2017). "We then used imaging mass cytometry (IMC) to detect CD2+MHC-II+CCR2+ myeloid precursors and CD200+ (DKK3+FAP+CD45−CD31−) fibroblasts in the synovial tissues of individuals with early PsA who had just developed arthritis and individuals with psoriasis without arthritis." (PMID 41482544, 2026).
glioblastoma (38 papers, 2017 to 2026). The most malignant astrocytic tumor (WHO grade IV). "Glioblastoma-associated FAP+ mesenchymal cells are localised around activated endothelial cells and their presence positively correlates with vascular density." (PMID 34282761, 2021). "Compared to normal brain, FAP was overexpressed at the gene and protein level in a large percentage of glioblastoma tissues, with highest levels of expression associated with poorer prognosis." (PMID 33082953, 2020). "Fibroblasts activating protein (FAP), a type II membrane-bound glycoprotein, is up-regulated in tumor-associated fibroblasts in more than 90 % of epithelial tumor and malignancies such as glioblastoma and lung cancer." (PMID 39839493, 2025). "Additionally, oncolytic adenoviruses (OAds) have been shown to target both glioblastoma cells and glioblastoma-associated stromal FAP+ cells, effectively disrupting tumor and stromal cell interactions." (PMID 39337402, 2024). "Also, FAP overexpressed in tumoral tissue compared to normal brain tissue, and its overexpression was associated with disease progression in glioblastoma." (PMID 37316886, 2023). "In this work, we introduce a vasoprobe-based cancer imaging strategy that targets the fibroblast-associated protein (FAP), an extracellular protease that is highly expressed in some glioblastomas, as well as tumorigenic stromal tissues (Puré and Blomberg, 2018)." (PMID 34931988, 2021). "Our IHC studies suggested that FAP could be expressed not only by glioblastoma cells themselves, but also by cells associated with tumor vessels." (PMID 33082953, 2020). "Intriguingly, these two molecules also show a perivascular distribution in glioblastoma and their expression is associated with the mesenchymal state, suggesting that FAP, EphA3 and α‐dystroglycan could be functionally linked." (PMID 33082953, 2020). "Fibroblast activating protein (FAP) is up-regulated in cancer-associated fibroblasts (CAFs) of more than 90 % of tumor microenvironment and also highly expressed on the surface of multiple tumor cells like glioblastoma, which can be used as a specific target for tumor diagnosis and treatment." (PMID 39839493, 2025). "FAP+ pericyte‐like cells drive the deposition of fibrillar extracellular matrix proteins such as collagen I and fibronectin in glioblastoma, facilitating glioma cell dissemination and activation of focal adhesion kinase." (PMID 38705944, 2024). "Elevated levels of the fibrillar proteins collagen I and fibronectin were associated with the expression of fibroblast activation protein (FAP), which is predominantly found in pericyte‐like cells in glioblastoma." (PMID 38705944, 2024). "Previously, the oncolytic adenovirus ICOVIR15 was shown to infect and kill fibroblast activation protein (FAP)+ fibroblasts in a murine glioblastoma model." (PMID 38037840, 2024). "These CAR‐T cells also controlled the growth of murine glioblastoma tumors without overt toxicity, even in the face of heterogeneous target antigen expression, suggesting FAP‐CAR‐T cells as a promising new approach for the treatment of glioblastoma." (PMID 38975278, 2024). "FAP expression is undetectable in glioblastoma cells in vitro but is expressed in vivo, including in tumour cells." (PMID 39629119, 2024). "An oAd, ICOVIR15, decreased the number of FAP+ pericytes, glioblastoma cells, and GMP-associated stromal FAP+ murine cells." (PMID 38256250, 2024). "In this study, we have developed a novel FAP‐targeting CAR and shown, for the first time, that FAP‐CAR‐T cells effectively destroy glioblastoma cells in vitro and in vivo." (PMID 38975278, 2024). "Animal studies have shown that fibroblast-activated protein (FAP) is over-expressed in vitro and in situ in glioblastoma (GBM) cells and tumor stroma especially in proximity to blood vessels." (PMID 39759219, 2024). "Glioblastoma is well‐known for its cellular heterogeneity, and we have shown that expression of FAP by glioblastoma tumor cells is also heterogenous." (PMID 38975278, 2024).
glioblastoma (continued). "We recently described fibroblast activation protein (FAP) as an ideal target antigen for glioblastoma immunotherapy, with expression on both tumor cells and tumor blood vessels." (PMID 38975278, 2024). "Studies from our group and others have shown that, in glioblastoma, FAP is heterogeneously expressed on tumor cells themselves, but more consistently by tumor‐supporting stromal populations including endothelial cells and pericytes." (PMID 38975278, 2024). "In glioblastoma, FAP has been proven to promote tumor growth and invasion via hydrolysis of molecules such as brevican in the extracellular matrix and targeting downstream pathways and substrates, such as fibroblast growth factor 21 (FGF21)." (PMID 37316886, 2023). "FAP-positive mesenchymal cells promote angiogenesis, glioma cell migration, and growth by paracrine communication, which leads to glioblastoma progression." (PMID 37316886, 2023). "Fibroblast activation protein alpha (FAP) promotes the progression of glioblastoma by remodeling the morphology of tumor cells and the phenotype of macrophages." (PMID 36382346, 2023). "In glioblastoma (one of the fatal cancers of the central nervous system), it is revealed that FAP-positive mesenchymal cells express pro-angiogenic factors." (PMID 37316886, 2023). "In epithelial cancers, FAP expression is largely limited to stromal cells although tumor cell expression of FAP has been reported in some epithelial cancer types including glioblastoma and uterine squamous cell carcinoma." (PMID 37333052, 2023). "This human glioblastoma cell–derived xenograft adequately recruits mouse fibroblasts during tumor growth and has been reported as a FAP-positive tumor model." (PMID 37321827, 2023). "[68Ga]Ga-DATA5m.SA.FAPi was assessed in vitro on FAP-expressing stromal cells, followed by biodistribution and in vivo imaging on prostate and glioblastoma xenografts." (PMID 37284857, 2023). "As a new diagnostic instrument, FAP-inhibitor (FAPI) PET imaging has found applications in a number of FAP-positive tumors, including glioblastoma." (PMID 36566187, 2022). "A previous study found that increased tracer uptake on FAP-specific imaging had the ability to distinguish isocitrate dehydrogenase (IDH)-wild-type glioblastomas and high-grade IDH-mutant astrocytoma." (PMID 34870727, 2022). "Concordantly with the FAP protein data reported in the present study, FAP mRNA was upregulated in glioblastomas compared to control brain tissues." (PMID 33494271, 2021). "In glioblastomas, FAP and TGFbeta-1 protein concentrations showed a weak but statistically significant positive correlation." (PMID 33494271, 2021). "Our previous work suggested increased expression of FAP, a potential TGFbeta target gene, in glioblastomas." (PMID 33494271, 2021). "In a previous study, we demonstrated increased expression of fibroblast activation protein (FAP) in a large proportion of human glioblastomas and its localization in both transformed and stromal cells." (PMID 33494271, 2021). "FAP+ mesenchymal cells derived from human glioblastomas are non-tumorigenic and mostly lack the cytogenetic aberrations characteristic of glioblastomas." (PMID 34282761, 2021). "We now extended the analysis of the TCGA data to 505 primary glioblastomas and analyzed the expression of FAP and individual TGFbeta isoforms." (PMID 33494271, 2021). "We detected TGFbeta-1 immunopositivity broadly in glioblastoma tissues, including tumor parenchyma regions in the immediate vicinity of FAP-immunopositive perivascular stromal cells." (PMID 33494271, 2021). "Among the various molecular subtypes of glioblastomas, we observed the highest FAP expression in the mesenchymal subtype." (PMID 33494271, 2021). "Our results provide insight into the previously unrecognized regulation of FAP expression by autocrine and paracrine TGFbeta-1 signaling in a broad spectrum of cell types present in the glioblastoma microenvironment." (PMID 33494271, 2021).